DST (dystonin)
Diseases named in the same sentence as DST in open-access papers (continued):
Sharing a sentence is not in itself a finding about the gene and the disease.
neuroblastoma (1 paper, 2021). Neuroblastoma (NB) is the most common solid, extracranial childhood tumor. "However, the functions of DST in neuroblastoma are barely known." (PMID 34116676, 2021). "Interestingly, high expression levels of ALCAM, CACNA2D3, DST, EPB41L4A or KIF1B were not only associated with the prognosis of MYCN non-amplified neuroblastoma patients, but also were associated with the prognosis of all neuroblastoma patients." (PMID 34116676, 2021). "Neuroblastoma patients with higher expression levels of ALCAM, CACNA2D3, DST, EPB41L4A or KIF1B had better clinical overall survival in TARGET dataset, GSE49710 dataset and GSE85047 dataset." (PMID 34116676, 2021). "The prognostic effects of age related genes ALCAM, CACNA2D3, DST, EPB41L4A and KIF1B in pediatric neuroblastoma patients were determined by Kaplan-Meier survival." (PMID 34116676, 2021). "And the higher expression levels of ALCAM, CACNA2D3, DST, EPB41L4A or KIF1B were associated with better prognosis of MYCN non-amplified neuroblastoma patients." (PMID 34116676, 2021). "Next, we tried to determine the associations of ALCAM, CACNA2D3, DST, EPB41L4A and KIF1B in MYCN non-amplified neuroblastoma patients." (PMID 34116676, 2021). "We found that ALCAM, CACNA2D3, DST, EPB41L4A and KIF1B were associated with the favorable prognosis of MYCN non-amplified neuroblastoma patients." (PMID 34116676, 2021). "ALCAM, CACNA2D3, DST, EPB41L4A and KIF1B were highly expressed in MYCN non-amplified younger neuroblastoma patients." (PMID 34116676, 2021). "MYCN non-amplified neuroblastoma patients with lower expression levels of ALCAM, CACNA2D3, DST, EPB41L4A or KIF1B were with lower overall survival in TARGET dataset, GSE49710 dataset and GSE85047 dataset." (PMID 34116676, 2021). "MYCN non-amplified neuroblastoma is a heterogeneous disease and could be divided into sub-groups based on age or the expression levels of ALCAM, CACNA2D3, DST, EPB41L4A and KIF1B." (PMID 34116676, 2021). "Furthermore, using multivariate cox regression, we determined the correlations of age, ALCAM, CACNA2D3, DST, EPB41L4A or KIF1B expression in the prediction of the clinical overall survival of MYCN non-amplified neuroblastoma patients." (PMID 34116676, 2021).
neuropathy (1 paper, 2018). A disorder affecting the nervous system that manifests with pain, tingling, numbness, and/or muscle weakness. "In humans,DST mutations, affecting distinct BPAG1 isoforms, lead to two autosomal-recessive disorders: (a) neuropathy, hereditary sensory and autonomic, type VI (MIM 614653) and (b) EB simplex, autosomal recessive 2 (MIM 615425)." (PMID 29568501, 2018).
prostate carcinoma (1 paper, 2016). A carcinoma that arises from epithelial cells of the prostate gland. "In addition, although the number and function of downregulated genes seemed to be less relevant than those upregulated, however we have identified that some of them also appear downregulated in prostate cancer (DST; VAV3; PLK3HH2; ITG6B; PPM1L)." (PMID 27732959, 2016).
psychosis (1 paper, 2017). "For the two other antigens, DST (dystonin) and AIDA (axin interactor, dorsalization associated), seroreactivity was more prevalent in the non-psychotic controls compared to patients with first-episode psychosis." (PMID 28742074, 2017).
pulmonary atresia (1 paper, 2022). "Recently, DST was reported as a candidate gene of pulmonary atresia, a rare congenital heart defect." (PMID 35942699, 2022).
sarcopenia (1 paper, 2025). Progressive decline in muscle mass due to aging which results in decreased functional capacity of muscles. "For example, in primary sarcopenia, ST detects IGF1 downregulation in Type I fibers together with DST, GATM, and PLIN4 upregulation in Type II fibers, indicating parallel anabolic failure in slow fibers and stress-induced cytoskeletal and metabolic remodeling in fast fibers." (PMID 40718353, 2025).
squamous cell carcinoma of the lung (1 paper, 2010). "Furthermore, DST has been shown to be perturbed in studies of other cancers, such as squamous cell carcinoma of the lung, making it an interesting target of further study." (PMID 20174472, 2010).
triple-negative breast carcinoma (1 paper, 2019). An invasive breast carcinoma which is negative for expression of estrogen receptor (ER), progesterone receptor (PR), and human epidermal growth factor receptor 2 (HER2). "Higher YAP activity due to the loss of DST could, in turn, initiate a positive feedback loop, which sustains its activity, as inhibiting YAP function in the triple-negative breast cancer cell line CAL51 upregulates DST and reduces Zyxin accumulation." (PMID 31882643, 2019).
tumor (25 papers, 2010 to 2025). "In contrast, the expression of genes such as CXCL12 (C-X-C motif chemokine ligand 2) and DST (dystonin) exhibited an increase in TR in most normal tissues compared to tumor samples." (PMID 39349823, 2024). "Our observations suggest that the BPAG1eA and/or BPAG1e isoforms endorse the tumour suppressor function of DST." (PMID 31882643, 2019). "To determine if DST acts as a bona-fide tumour suppressor, we generated stable MCF10A cells carrying Tet-inducible shRNA against all DST isoforms (shDST)." (PMID 31882643, 2019). "Extensive search of the literature revealed a potential key role of genes at the identified porcine loci in tumor invasion (DST, PLEKHA5, CBY1, LIMK2 and ETV5) and immune response modulation (ETV5, HERC3 and DICER1) of the progression phenotypes." (PMID 29963229, 2018). "Our observations are consistent with a model by which the tumour suppressor function of DST could be restricted to the shorter DST isoforms BPAG1eA and/or BPAG1e." (PMID 31882643, 2019). "We show that DST has tumour suppressor activity in breast epithelial cells." (PMID 31882643, 2019). "Here, we provide a molecular mechanism for the tumour-suppressing function of DST." (PMID 31882643, 2019). "DST and AHNAK genes that were significant from the stage III survival analysis have shown tumour suppressive characteristics in both experimental and computational BC studies." (PMID 36765262, 2023). "We confirmed an aberrant increase of cassette exon skipping in tumor specimens for PACSIN2 exon 8, DIAPH1 exon 2, FGFR1OP2 exon 4, MARK3 exon 16, DST exon 93, LMO7 exon 10, and RBM5 exon 7, whereas ADD3 exon 13, MAP3K7 exon 12, and MARK2 exon 15 were preferentially included in tumor specimens." (PMID 34202984, 2021). "Similarly, we found switches in genes involved in cell communication pathways, including DST and FLNA, which could be used for developing tumor-specific molecular targets with reduced cross-reactivity to other proteins." (PMID 25578962, 2015).
cancer (22 papers, 2010 to 2025). A tumor composed of atypical neoplastic, often pleomorphic cells that invade other tissues. "Aberrant expression and/or splicing of DST (also known as BPAG1), TEAD1 and THOC5 are associated with neurological disorders and cancer." (PMID 37026480, 2023). "Aberrant expression of the Spectraplakin Dystonin (DST) has been observed in various cancers, including those of the breast." (PMID 31882643, 2019). "However, we cannot exclude that distinct DST isoforms have opposite effects in cancer progression." (PMID 31882643, 2019). "Further validation in four independent cohorts showed that KEAP1, SRI, MFAP1, MFAP2, INCENP, and KIF21B were consistently upregulated in cancer tissues, while MYOZ3, DST, and TIAM1 were consistently downregulated." (PMID 40228435, 2025). "Heatmap results showed that NRP1, MFAP2, KLC1, DST, and MYOZ3 were generally downregulated in cancer cell lines, while KIF21B, SRI, INCENP, and KEAP1 were also downregulated." (PMID 40228435, 2025). "In invasive ductal breast carcinoma, the cancer cell expression of the protease inhibitor, CSTA and genes involved in adhesion, FAT1, DST, and TMEM45A, were shown to be involved in cancer invasiveness." (PMID 36114508, 2022). "Thus, in cancer cells, DST function could be context dependent." (PMID 31882643, 2019). "Several of these genes are related to cancer, including CD44, DST, GLS, GNAS, KIF1B and AHRR." (PMID 34086943, 2021). "In addition, cancer cells in SN upregulated MT-RNR2, DST, and MALAT1." (PMID 37745301, 2023).
neurological diseases (14 papers, 2013 to 2025). "Dystonin (also known as bullous pemphigoid antigen-1) connects IFs and microtubules, and mutations in dystonin have been linked to neurological disorders and skin blistering." (PMID 36398718, 2022). "FSD mice presented here are most akin to human dystonin induced EBS patients without nervous system disorders, which all have mutations in DST-e specific exon 23 (called hu-ex23), and contrast sharply with EBS+DM." (PMID 37883475, 2023).
neurodegenerative disease (2 papers, 2018 to 2024). A disorder of the central nervous system characterized by gradual and progressive loss of neural tissue and neurologic function. "Three of the genes upregulated by Aβ + homogenate challenge are expressed in neurons and implicated in neurodegenerative diseases (DYS—dystonin, SACS—sacsin, and VPS13C—vacuolar protein sorting 13)." (PMID 38319380, 2024).
movement disorder (1 paper, 2012). Neurological conditions resulting in abnormal voluntary or involuntary movement, which may impact the speed, fluency, quality and ease of movement. "Mutations in the dystonin (Dst) gene in mice result in a movement disorder phenotypically resembling some aspects of early-onset torsion dystonia in humans." (PMID 22611399, 2012).
skin disorder (1 paper, 2025). Any deviation from the normal structure or function of the skin or subcutaneous tissue that is manifested by a characteristic set of symptoms and signs. "BP is a highly debilitating skin disorder that typically affects the elderly and is characterized by a distinctive eosinophilic infiltration and the presence of immunoglobulin (Ig) and IgE autoantibodies to BP180 (collagen XVII) and BP230 (dystonin)." (PMID 40649854, 2025).
DST also shares sentences with these, for which no sentence is quoted: pemphigoid (17 papers); Autoimmunity (8); Pruritus (6); mucous membrane pemphigoid (5); multiple sclerosis (4); pemphigus (4); eosinophilia (3); Parkinson disease (3); Ataxia (2); COVID-19 (2); Erythema (2); essential hypertension (2); glioma (2); infection (2); pemphigoid gestationis (2); psoriasis (2); urticaria (2); anhidrosis (1); Arthritis (1); autoimmune liver disease (1); cardiovascular diseases (1); cerebral infarction (1); cerebrovascular disease (1); cervical cancer (1); chronic GvHD (1); chronic spontaneous urticaria (1); colorectal tumors (1); dementia (1); eczema (1); epidermoid carcinoma (1).
A further 28 diseases each share a sentence with DST in 1 paper.